IFNAR2 (interferon alpha and beta receptor subunit 2)
Diseases named in the same sentence as IFNAR2 in open-access papers (continued):
Sharing a sentence is not in itself a finding about the gene and the disease.
hepatitis B (2 papers, 2010 to 2012). "The present study aimed to investigate the role of HBV genotypes and IFNAR2 in response to Peg-IFN-α-2a in Chinese patients with hepatitis B. Until now, based on an intergroup divergence of 8 % or more in the complete nucleotide sequence, HBV can be classified into nine genotypes (A-I)." (PMID 22783345, 2012).
Hypertension (2 papers, 2023 to 2025). The presence of chronic increased pressure in the systemic arterial system. "Logistic regression analysis under five genetic models adjusted for age, sex, smoking history, DM, hypertension, and CAD was used to investigate the role of IFNAR2 rs2236757 and OAS3 rs10735079 polymorphisms in the susceptibility of COVID-19 infection and severity." (PMID 37745867, 2023).
metastatic tumor (2 papers, 2007 to 2024). "In 2002, a metastatic tumor was found that involved the thyroid gland, and we determined that it also had a high level of IFNAR2 mRNA expression (1.13 fold more than the second primary tumor)." (PMID 17697365, 2007). "TempO-Seq analysis showed upregulation of innate immune response and IRF pathway genes (IRF1, IRF7, IFNAR2, JAK1, STAT1), yet no reduction was observed in the metastatic tumors." (PMID 38516270, 2024).
rheumatoid arthritis (2 papers, 2017 to 2023). A chronic, systemic autoimmune disorder characterized by inflammation in the synovial membranes and articular surfaces. "In Mendelian randomization, the expression of IFNGR2 (beta=− 0.12, SE=0.02, PIVW= 7.78E − 12) and IFNAR2 (beta=− 0.08, SE=0.03, PIVW=0.004) in blood cells were negatively associated with the risk of rheumatoid arthritis." (PMID 37019979, 2023).
SARS-CoV infections (2 papers, 2022 to 2026). "All in all, results suggest that the carriage of IFNAR2 p.F8S is associated with upregulation of a transcriptional program sustaining immune response following SARS-CoV-infection." (PMID 41596638, 2026). "IFNAR2, TLR7 and JAK1 genes connect SARS-CoV infections and potential therapeutics for SARS." (PMID 36553678, 2022).
Autoimmunity (1 paper, 2009). The occurrence of an immune reaction against the organism's own cells or tissues. "It will therefore be critical to assess the function of TAM receptors and the differential roles of IFNAR1 and IFNAR2 in the development of autoimmunity." (PMID 19624844, 2009). "We hypothesize that the lack of negative regulatory molecule function in IFNAR1-/- mice may result in phenotypic differences between IFNAR1-/- and IFNAR2-/- mice in models of autoimmunity." (PMID 19624844, 2009).
brain tumor (1 paper, 2025). "Colocalization analysis identified rs1476415 (within -/+ 500kb of IFNAR2) meeting stringent colocalization criteria (SNP.PP.H4 > 0.9), suggesting this locus may regulate IFNAR2 expression to mediate brain tumor pathogenesis." (PMID 41169364, 2025).
chronic hepatitis B infection (1 paper, 2012). "HBV genotype B and high expression of IFNAR2 in the liver of chronic hepatitis B patients are closely associated with better response to Peg-IFN-α-2a therapy in chronic hepatitis B disease." (PMID 22783345, 2012). "This study in conducted to investigate the influence of Hepatitis B virus (HBV) genotypes and type I IFN-αreceptor β subunit (IFNAR2) expression in liver on response to treatment with pegylated IFN-α-2a (Peg-IFN-α-2a) for chronic hepatitis B infection." (PMID 22783345, 2012). "In addition to HBV genotype factor, our study investigated whether expression levels of IFNAR2 in the liver of chronic hepatitis B patients are correlated with the response to Peg-IFN-α-2a therapy." (PMID 22783345, 2012).
Cirrhosis (1 paper, 2012). A chronic disorder of the liver in which liver tissue becomes scarred and is partially replaced by regenerative nodules and fibrotic tissue resulting in loss of liver function. "Genes involved in cirrhosis development (ABCG2, CTNNB1, B2M, IFNAR1, IFNAR2), and hepatic cholestasis (CYP7B1) were found significantly down-regulated in patients without HCC." (PMID 22792259, 2012).
co-infection (1 paper, 2019). "The selective function of IFNβ in our co-infection model is supported by data on its ability to bind to IFNAR1 in an IFNAR2 independent manner activating a unique set of genes in LPS shock." (PMID 31500303, 2019).
Hemophagocytic Lymphohistiocytosis (1 paper, 2020). "We describe a 2 year old boy with two previously undescribed frameshift mutations in the interferon (IFN)α/β receptor 2 (IFNAR2) gene presenting with hemophagocytic lymphohistiocytosis (HLH) following measles-mumps-rubella vaccination." (PMID 33193576, 2020).
hepatocellular carcinoma (1 paper, 2009). A malignant tumor that arises from hepatocytes. "Type I IFN receptor type 2 (IFNAR2) expression correlates significantly with clinical response to interferon (IFN)-α/5-fluorouracil (5-FU) combination therapy for hepatocellular carcinoma (HCC)." (PMID 19401692, 2009).
herpesvirus infection (1 paper, 2025). "KEGG pathway analysis indicated that IFNAR2 is significantly enriched in the Kaposi sarcoma-associated herpesvirus infection pathway." (PMID 39943096, 2025). "The results of functional enrichment analyses suggest that the IFNAR2 gene may regulate exercise-induced inflammatory responses through the binding term and the Kaposi sarcoma-associated herpesvirus infection pathway, thereby maintaining cellular homeostasis and normal physiological function." (PMID 39943096, 2025).
Hurler disease (1 paper, 2012). "In MPS I mice (a model of Hurler disease caused by alpha-L-iduronidase deficiency) both HS and DS accumulate and the mice have similar changes in microglial activation genes as MPS IIIb; however, genes associated with inflammation are not up-regulated (e.g. Ifitm1, Ifnar2 )." (PMID 22403656, 2012).
Immunodeficiency (1 paper, 2022). Failure of the immune system to protect the body adequately from infection, due to the absence or insufficiency of some component process or substance. "Mutations in IFNAR2 are associated with Immunodeficiency and measles virus susceptibility and play an essential and a narrow role in human antiviral immunity." (PMID 36424512, 2022).
laryngeal carcinoma (1 paper, 2024). Carcinoma that arises from the laryngeal epithelium. "In summary, our research suggests that the exacerbation of COVID-19 infection may be an important factor in reducing the risk of laryngeal cancer, and the increase in IFNAR2 levels may play a significant role in this." (PMID 38915416, 2024). "Maintaining high expression of IFNAR2 and restoring normal levels of type I interferon can effectively inhibit the proliferation of tumor cells, thereby reducing the risk of laryngeal cancer or improving the treatment effect of laryngeal cancer patients during IFN treatment." (PMID 38915416, 2024).
liver cancer (1 paper, 2023). An epithelial or non-epithelial malignant neoplasm that arises from the liver. "Also in another human liver cancer cell line, downregulation of IFNAR2 was previously reported upon long-term exposure to type I IFN, however with no clear correlation to proliferation or cell viability." (PMID 38066598, 2023).
medulloblastoma (1 paper, 2025). A malignant, invasive embryonal neoplasm arising from the cerebellum. "All immune cells express receptors for TNF-alpha (TNFRSF1A and TNFRSF1B) and IFN alpha (IFNAR1 and IFNAR2) and are enriched for these pathways, indicating that all these immune cell types are primed to respond to secreted TNF-alpha and IFN alpha in the medulloblastoma TME." (PMID 40240536, 2025).
metastatic melanoma (1 paper, 2022). A melanoma that has spread from its primary site to another anatomic site. "Although all the IFNA transcripts were barely detectable, high levels of IFNAR1 and IFNAR2 expression were observed in both primary and metastatic melanoma." (PMID 35145233, 2022).
migraine (1 paper, 2021). "IFNAR2 was associated with migraine (OR = 1.35; p value = 4.10E-06) and with throat pain (OR = 2.05; p value = 2.62E-05)." (PMID 34315903, 2021).
osteoporosis (1 paper, 2022). A condition of reduced bone mass, with decreased cortical thickness and a decrease in the number and size of the trabeculae of cancellous bone (but normal chemical composition), resulting in increased fracture incidence. "After construction the miRNA-gene interaction network, we identified 6 hub miRNAs (hsa-miR-18b-3p, hsa-miR-361-3p, hsa-miR-484, hsa-miR-519e-5p, hsa-miR-940, and hsa-miR-1275) and 6 hub genes (THBS1, IFNAR2, ARHGAP5, TUBB2B, FLNC, and NTF3) for osteoporosis." (PMID 35757478, 2022). "And in our study, for the first time, the intimate association of the other 3 miRNAs (hsa-miR-18b-3p and hsa-miR-519e-5p) and 4 genes (IFNAR2, ARHGAP5, FLNC, and NTF3) with osteoporosis was discovered." (PMID 35757478, 2022).
plasmacytoma (1 paper, 2009). Plasmacytoma is a localized mass of neoplastic monoclonal plasma cells that represents approximately 5% of all plasma cell neoplasms. "Third, IRF9-/- mice treated with pristane developed fatal plasmacytomas as early as 6 months following pristane injection, whereas no IFNAR2-/- mice developed this phenotype." (PMID 19624844, 2009).
prion disease (1 paper, 2010). A transmissible disease that is caused by a protein that is able to induce abnormal folding of normal cellular proteins, leading to characteristic spongiform brain changes, which are associated with neuronal loss without an inflammatory response. "IFNAR2 was induced by prion disease (main effect of disease: F = 107.98, df 1, 12, p < 0.0001) but is not significantly affected by poly I:C (F = 0.79, df 1, 12, p = 0.39)." (PMID 20399848, 2010).
sarcoma (1 paper, 2020). A usually aggressive malignant neoplasm of the soft tissue or bone. "Similarly, IFNAR2-deficient sarcoma cells (Ifnar2−/−) failed to secrete IFN type I upon doxorubicin stimulation." (PMID 33182724, 2020).
infection (77 papers, 2010 to 2026). The state of being infected such as from the introduction of a foreign agent such as serum, vaccine, antigenic substance or organism. "The results indicated that LSDV-encoded LSDV122 was associated with endogenous IFNAR1 and IFNAR2 following infection in MDBK cells." (PMID 41525414, 2026). "Other studies also suggested an association between IFNAR2 rs2236757 and rs1051393 and susceptibility to infection with the omicron variant of the SARS-CoV-2 virus." (PMID 39435115, 2024). "IFNAR2 has indeed been repeatedly associated with an increased risk of hospitalization post-infection and disease severity, yet with more marginal ORs unlikely compatible with severe IEIs." (PMID 35768520, 2022). "For SARS-CoV-2 susceptibility, rs2229207 (TC genotype, allele C) and rs17860118 (allele T) of IFNAR2 increased the risk of infection, but rs139940581 (CT genotype, allele T) of SLC6A20 reduced virus sensitivity." (PMID 36292769, 2022). "The protein coded by IFNAR2 forms a part of membrane receptor for interferons eventually leading to the phosphorylation of many proteins typically associated with infection prevention." (PMID 31034533, 2019). "Variants in IFNAR1 and IFNAR2 could potentially be new targets for therapies that limit the infection and the resulting inflammation by SARS-CoV-2 infection." (PMID 38003785, 2023). "IFNAR2 levels remained essentially constant throughout the infection and were similar to the uninfected controls." (PMID 40558091, 2025). "During the initial phase, hyper-response to IFN-I due to triplication of IFNAR1 and IFNAR2 sensitizes the cells to an antiviral state, resulting in reduced infection by influenza A virus." (PMID 38540156, 2024). "The inhibition of AdV-C5 infection with miR-29b-1* mimic depended on the IFN-alpha receptor 2 (IFNAR2) and the RNA-helicase retinoic acid-inducible gene I (RIG-I) but not cytoplasmic RNA sensors MDA5 and ZNFX1 or MyD88/TRIF adaptors." (PMID 35891387, 2022). "Next, we evaluated the functional role of IFNAR2 in inhibiting ZIKV replication in vivo by conducting animal infection experiments." (PMID 36246651, 2022). "A breeding herd of 32 IFNAR2+/− ewes, which are fertile, has been developed for production of IFNAR2−/− sheep for both infection and reproduction studies." (PMID 36246651, 2022). "Apl-miR-455-5p and apl-miR-499-3p which targeted IFNAR1, plus novel-m0213-5p which targeted IFNAR2 were significantly down-regulated after DHAV-3 infection." (PMID 32019511, 2020). "Influenza A was also shown to downregulate IFNAR1 and IFNAR2 in human monocyte-derived macrophages, however ex vivo infection of human lung tissue with Influenza A only reduced the expression of IFNAR1, but not IFNAR2." (PMID 31935222, 2020). "Perhaps additional time points after infection are necessary to detect significant changes in IFNAR2 expression when using the LPAC model." (PMID 31935222, 2020). "Notably, pitavastatin-mediated enhancement of IFN-β mRNA expression following Flu infection was markedly reduced by IFNAR2 KO." (PMID 39668245, 2025). "Consequently, infection of IFNAR2-/- iPS-Mφ with ZIKVFP recapitulated the enhanced permissiveness to infection and CPE previously observed in IFNAR2PT iPS-Mφ, confirming the association of the observed phenotypes with defective IFNAR signalling." (PMID 36439115, 2022). "However, the MPL16 strain was more efficient than L. plantarum CRL1506 in increasing DDX58 and IFNAR2 at hour 12 post-infection." (PMID 34578229, 2021). "At first glance the triplication of IFNAR1 and IFNAR2, with consequent upregulation of the anti-viral Type I interferon signaling, might suggest higher defenses in DS individuals in a first stage of the infection." (PMID 33479353, 2021). "In this study, we aimed to determine whether the different responses are based on differential expression of IFNAR2 on various immune cell populations and if receptor expression levels might be altered upon infection with HIV." (PMID 31935222, 2020).
infection (continued). "Several variants (rs17763742 near LZTFL1, rs2834164 in IFNAR2 and rs1826292621 near TLE1) showed a significant difference in effect sizes (SNP*sex interaction P < 0.0031, adjusted probability for 16 comparisons) linked not only to hospitalization, but also to critical illness and infection risk." (PMID 35708486, 2022). "The Sankey diagram of IFN and receptor genes showed that Type I interferon (IFN-α) and its receptor genes (IFNAR1 and IFNAR2), Type II interferon (IFN-γ) and its receptor gene (IFNGR) were upregulated post-infection." (PMID 40469055, 2025). "Substantiating this observation, post-IAV-infection, there was a significant decrease in TRIM71 and IFNAR2 protein levels." (PMID 40219968, 2025). "Using single-cell RNA-sequencing (scRNA-seq), we measured the expression of either type I (Ifnar1 and Ifnar2) or type III (Ifnlr1 and Il10rb) IFN receptor subunits in mouse lung cells on day 1 post-infection." (PMID 38530032, 2024). "In contrast, GSK 872 treatment significantly blunted infection-induced upregulation of IFN receptor subunits, including the type I IFN receptor subunits Ifnar1 and Ifnar2, and the type II IFN receptor subunits Ifngr1, and Infgr2." (PMID 38011306, 2023). "Single-nucleotide variants in the IFNAR1 and IFNAR2 genes potentially affect the immune response, exacerbate, or attenuate the disease in the face of SARS-CoV-2 infection, in addition, could be new targets for therapies that limit the infection and the resulting inflammation." (PMID 38003785, 2023). "The expression of type I (IFNAR1 and IFNAR2) and II (IFNGR1) receptors were suppressed in VSV-infected cells compared to mock-infection." (PMID 34578166, 2021). "The results demonstrated that infection of wild-type LSDV but not LSDVΔ122 reduced IFN-β-induced endogenous association between IFNAR1 and IFNAR2." (PMID 41525414, 2026). "Over the course of infection, IFNAR1 and IFNGR1 decreased, whereas IFNAR2 remained stable." (PMID 40558091, 2025). "In the same study, infection of moMΦ with Georgia 2007 strain down-regulated other receptors, such as interferon receptors (IFNAR1, IFNAR2, IFNGR) and interleukin receptors (IL4R, IL10RA, IL10RB, and IL17RA), as well as transcriptomic factors (e.g., FOS, JUN, and TBK1)." (PMID 40530033, 2025). "The results showed the mean percentage of infected cells reached 87.2% upon 2280 infection at an MOI of 1 at 16 hpi, and the surface expression of IFNAR1 but not IFNAR2 was significantly downregulated by nearly 24% upon FCV 2280 infection." (PMID 33075108, 2020). "Moreover there is a group of molecules, including LTA, LTB, IL21, IFNAR2, CXCR3, IL17F and CD40LG, whose expression increased over the course of USA300 infection." (PMID 25719526, 2015). "Finally, in the isogenic fibrosarcoma U5A, cells that lack the IFNAR2 chain of the Type I IFN receptor and are insensitive to any Type I IFN, infection with HSV robustly induced Ser535 phosphorylation of IFNAR1." (PMID 21695243, 2011). "In the IFNAR2-KO cells AdV-C5 infection was no longer attenuated by miR29b-1* mimic and indistinguishable from Rand transfection Likewise, reduction of cell numbers was less pronounced, suggesting that the effect on cell viability/growth was due to IFN response, rather than general toxicity." (PMID 35891387, 2022). "To explore whether SECoVs infection affects IFN receptors expression, we next compared the receptor expression of the three types of IFNs, including type I IFN receptors (IFNAR1 and IFNAR2), type II IFN receptors (IFNGR1 and IFNGR2), and type III IFN receptors (IL10RB and IFNLR1)." (PMID 35126380, 2021). "Since we could not observe any difference in IFNAR2b/c surface expression following HIV-infection, we next analyzed the expression of soluble IFNAR2 (sIFNAR2a) in the supernatant of mock-treated and HIV-infected LPMCs at days 1, 4 and 7 post infection via ELISA." (PMID 31935222, 2020).
infection (continued). "Furthermore, while IFNAR2 blockade (which repressed the IFNβ-IRF7 forward feedback loop) did not affect the expression pattern in the high MOI infection, it significantly repressed all subtypes except IFNα1, -α2, and -α8 after low MOI infection." (PMID 33542718, 2020). "However, in RoNi cells, higher IFNAR levels, especially soluble IFNAR2—a putative potentiator of quicker more sustained responses—could enable strong IFN-independent, IRF-mediated ISG15 induction, allowing cells to engage a core aspect of the ISGylation pathway in advance of the infection." (PMID 30400182, 2018). "However, Ifnar1 and Ifnar2 were lowly expressed in IFN-act TN (T8) cells; therefore, we indicated that IFN-act TN cells possibly secrete type I IFN after infection with E. granulosus and produce a nonpreferential immune response." (PMID 37039643, 2023).